ARSB (arylsulfatase B)
Diseases named in the same sentence as ARSB in open-access papers (continued):
Sharing a sentence is not in itself a finding about the gene and the disease.
mucopolysaccharidosis (9 papers, 2012 to 2023). A group of autosomal recessive or X-linked inherited lysosomal storage disorders affecting the metabolism of mucopolysaccharides, resulting in the accumulation of mucopolysaccharides in the body. "Arylsulfatase B (ARSB) was first described in the mid-20th century when it was identified in human liver and subsequently associated with MLS or Mucopolysaccharidosis (MPS) VI, as summarized by McKusick." (PMID 36361933, 2022).
melanoma (7 papers, 2017 to 2026). A malignant, usually aggressive tumor composed of atypical, neoplastic melanocytes. "Decline in ARSB was associated with malignancy in mammary, colon, and prostate cells and tissues as well as in melanoma." (PMID 40562100, 2025). "In prior work, a decline in ARSB was associated with the increasing invasiveness of human melanoma cell lines, as well as with more aggressive human prostate and colonic cancers and with malignant mammary cells." (PMID 38892038, 2024). "Attention to ARSB and chondroitin 4-sulfate-mediated regulation of transcriptional events provides an innovative approach to address the underlying molecular basis of melanoma progression." (PMID 37813168, 2024). "Increased expression of pro-MMP2 and MMP-9 occurred in melanoma cell lines following ARSB silencing, and these increases were associated with increased invasiveness." (PMID 36361933, 2022). "A375 melanoma cells were exposed to exogenous ARSB (1 ng/ml x 24h) or silenced by ARSB siRNA; duplicate samples were analyzed for total content of chondroitin sulfates (CS), heparan sulfates (HS), and hyaluronan (HA)." (PMID 40562100, 2025). "In normal melanocytes and B16F10 melanoma cells, similar effects of ARSB treatment on CHST15 and CHST11 expression were detected." (PMID 40562100, 2025). "In this report, the impact of ARSB on the progression of metastatic, pulmonary B16F10 melanomas in C57BL/6J mice is addressed, and the underlying apoptotic mechanism by which ARSB inhibits melanoma growth is identified." (PMID 40562100, 2025). "In our efforts to determine how ARSB-induced changes in chondroitin sulfates links to melanoma apoptosis, disaccharide analysis provides an indirect method." (PMID 40562100, 2025). "In this project, following treatment with recombinant human ARSB in the syngeneic B16F10 mouse model of subcutaneous melanoma and in the human A375 melanoma cell line, expression of CSPG4 declined significantly, suggesting another approach to inhibit CSPG4." (PMID 37813168, 2024). "Treatment of the melanoma tumors with exogenous ARSB increased the active phospho-SHP2, attributable to decline in SHP2 bound with C4S." (PMID 37813168, 2024). "Locally administered, exogenous ARSB markedly inhibited the growth of subcutaneous malignant melanomas in the B16F10 syngeneic mouse model in young, female C57BL/6J mice." (PMID 37813168, 2024). "The epigenetic mechanism in the melanoma cells affecting PD-L1 expression resembles the previously observed mechanisms by which ARSB and chondroitin 4-sulfation affect galectin-3 and AP-1, as shown by transcriptional effects on HIF-1α, Wnt9a, and versican." (PMID 38892038, 2024). "Experiments in the human melanoma cell line A375 demonstrated similar responses to exogenous ARSB as in the tumors, and inverse effects followed ARSB siRNA." (PMID 37813168, 2024). "In the syngeneic, subcutaneous B16F10 mouse model of malignant melanoma, treatment with exogenous ARSB markedly reduced tumor size and extended survival." (PMID 37813168, 2024). "Initial experiments showed that silencing ARSB in melanoma cells increased the expression of PD-L1 mRNA and protein and, inversely, treatment by exogenous ARSB reduced PD-L1 expression in human and mouse melanoma cells." (PMID 38892038, 2024). "The experiments detailed in this report were performed to clarify the mechanism by which ARSB regulated PD-L1 expression in the subcutaneous B16F10 mouse melanomas, in human A375 melanoma cells, and in normal human melanocytes." (PMID 38892038, 2024). "The treatment of the melanoma cells by methyl-β-d-xylopyranoside (BDX) produced similar effects as ARSB knockdown." (PMID 38892038, 2024). "The impact of exogenous ARSB on reducing their expression suggests another approach to inhibit the impact of the MMPs on melanoma progression." (PMID 37813168, 2024).
melanoma (continued). "Initial experiments in human melanoma cells (A375) showed that PD-L1 expression increased from 357 ± 31 to 796 ± 50 pg/mg protein (p < 10−11) when ARSB was silenced in A375 cells." (PMID 38892038, 2024). "Measurements of PD-L1 protein and mRNA were also performed following ARSB silencing or exposure to rhARSB (1 ng/mL × 24 h) in cultured normal human melanocytes and in A375 human melanoma cells." (PMID 38892038, 2024). "In the B16F10 melanoma tumor tissue and in the normal melanocyte (M0) and malignant A375 cells, the effects of exogenous ARSB and of ARSB and galectin-3 knockdown were evaluated." (PMID 38892038, 2024). "Recent work demonstrated that exogenous, bioactive ARSB reduced the progression and improved the survival of mice with B16F10 subcutaneous melanomas, and further evaluation of the potential therapeutic benefit of exogenous ARSB treatment is warranted." (PMID 38892038, 2024). "The cell-based results corroborate the measurements from the mouse melanomas and imply that the decline in tumor growth, and the resulting improvement in survival, are mediated by the impact of exogenous ARSB on chondroitin 4-sulfation." (PMID 37813168, 2024). "The decrease of ARSB activity resulted in the overexpression of melanoma progression factors, such as chondroitin sulfate proteoglycan 4 (CSPG4) and pro-matrix metalloproteinase 2 (pro-MMP2), causing increased invasiveness of melanoma cells." (PMID 37601653, 2023). "Other studies have identified increase in programmed death ligand 1 (PD-L1) following decline in ARSB by siRNA in the cultured melanoma cells and in melanoma tissue with reduced ARSB." (PMID 36361933, 2022). "In melanoma cells, decline in ARSB increased expression of MMP-9 and pro-MMP2 due to inhibition of SHP2 and activation of phospho-ERK1/2." (PMID 36361933, 2022). "In other experiments, PD-L1 gene and protein expression declined in B16F10 melanomas in C57BL/6J mice following treatment with recombinant ARSB (unpublished data)." (PMID 36361933, 2022). "In human malignant melanoma cell lines, ARSB activity declined progressively with increased invasiveness of the melanoma cell lines." (PMID 36361933, 2022). "Correspondingly, the chondroitin 4-sulfate increased, as ARSB declined from normal melanocytes to metastatic melanoma cells." (PMID 36361933, 2022). "ARSB was significantly lower in malignant tissue and malignant cell lines from colon, prostate, mammary, and melanoma than control samples." (PMID 36361933, 2022). "Recent work (unpublished) in melanoma cell lines reveals inverse effects of ARSB silencing and treatment by rhARSB on the activity of histone acetyltransferases (HAT) and on histone deacetylases (HDAC)." (PMID 36361933, 2022). "Invasiveness of the melanoma cells increased following ARSB silencing or treatment with the SHP2 inhibitor PHSP1 (p < 0.001)." (PMID 27926479, 2017). "The studies provide a basis for further assessment of the therapeutic impact of ARSB replacement on melanoma progression." (PMID 27926479, 2017). "Experiments were performed in melanoma cell lines to determine ARSB activity and impact on melanoma invasiveness." (PMID 27926479, 2017). "In this report, we present new mechanistic insights into how melanoma progression can arise in relation to decline in the enzyme arylsulfatase B, with concomitant increase in chondroitin 4-sulfation." (PMID 27926479, 2017). "The apparent synergism between effects of ARSB and Pembrolizumab may further inhibit the progression of melanoma and improve treatment outcomes." (PMID 42306793, 2026). "Combined treatment by recombinant human ARSB, directed at melanoma cells, and Pembrolizumab, directed at infiltrating cytotoxic lymphocytes, can lead to increased apoptosis by different mechanisms, to declines in metalloproteinases and invasiveness, and to altered expression of cytokines." (PMID 42306793, 2026).
melanoma (continued). "Treatment with rhARSB or by ARSB siRNA in A375 melanoma cells impacts cytokine production (unpublished data), suggesting that inflammatory mechanisms may also contribute to the rhARSB-induced enhancement of apoptosis and to other pathways of cell death." (PMID 40562100, 2025). "For this report, we performed disaccharide analysis of malignant human melanoma cells following treatment by exogenous ARSB and by ARSB siRNA and considered these findings about the measured effects of ARSB on chondroitin 4-sulfate and on carbohydrate sulfotransferase (CHST) expression." (PMID 40562100, 2025). "To explain the marked inhibition of melanoma proliferation, we considered whether exogenous ARSB could increase apoptosis of the melanomas." (PMID 40562100, 2025). "Inverse to the impact of exogenous ARSB and pertinent to the development of melanoma, ARSB silencing increased CHST15 expression, abundance of C4,6S disaccharides, and activation of phospho(Tyr)-ROR1 and phospho(Ser473)-AKT1 and reduced nuclear FOXO3a and COP1 expression." (PMID 40562100, 2025). "In addition to impact on CSPG4 expression, treatment of the mouse melanomas with exogenous ARSB increased the activity of SHP2, attributable to less binding of SHP2 with C4S following ARSB, as previously." (PMID 37813168, 2024). "In subcutaneous B16F10 murine melanomas, PD-L1 declined from 1227 ± 189 to 583 ± 110 pg/mg protein (p = 1.67 × 10−7), a decline of 52%, following treatment with exogenous, bioactive recombinant ARSB." (PMID 38892038, 2024). "Prior work in human melanoma cell lines detected increased expression of CSPG4, also known as melanoma-associated chondroitin sulfate proteoglycan (MCSP) or neuron-glial antigen 2 (NG2), when ARSB activity was reduced." (PMID 37813168, 2024). "Exogenous ARSB acted on melanoma cells and normal melanocytes through the IGF2 receptor." (PMID 38892038, 2024). "In the cultured A375 human melanoma cells, silencing ARSB and exogenous ARSB had inverse effects." (PMID 37813168, 2024). "The findings that follow support the impact of ARSB and chondroitin 4-sulfation on galectin-3, c-Jun, HDAC3, and H3 on the regulation of PD-L1 expression in melanoma and suggest that ARSB may help with checkpoint inhibition." (PMID 38892038, 2024). "In melanoma cells, ARSB activity was decreased compared to normal melanocytes." (PMID 37601653, 2023). "In addition to the observed effects on mRNA expression of CSPG4 and pro-MMP2, the expression of another gelatinase, MMP9, was also increased in the malignant melanoma cells and following silencing of ARSB." (PMID 27926479, 2017). "Combined effects of increased C4S, CSPG4, and MMP2 increased the invasiveness of the melanoma cells, and therapy with recombinant ARSB may inhibit melanoma progression." (PMID 27926479, 2017). "ARSB, which removes the 4-sulfate group at the non-reducing end of C4S, acts as a tumor suppressor, and treatment with exogenous ARSB impacts on vital cell signaling and reduces the expression of critical genes associated with melanoma progression." (PMID 37813168, 2024). "In this report, we present the signaling and transcriptional events initiated by arylsulfatase B (ARSB; N-acetylgalactosamine-4-sulfatase), which lead to COP1-mediated apoptosis of melanoma cells." (PMID 40562100, 2025). "In this report, we address how treatment by recombinant human ARSB impacts on apoptosis of melanoma by COP1 and identify a pathway by which ARSB-induced changes in chondroitin sulfation regulate COP1 expression." (PMID 40562100, 2025). "In the subcutaneous mouse melanoma tissue, HDAC3 activity increased following exogenous ARSB (p < 0.0001), in contrast to the decline in free galectin-3." (PMID 38892038, 2024). "In cultured, human malignant melanoma cells, the expression of the enzyme N-acetylgalactosamine-4-sulfatase (Arylsulfatase B; ARSB) declined with the increasing invasiveness of a series of seven human melanoma cell lines." (PMID 37813168, 2024).
melanoma (continued). "The recombinant, human ARSB was previously shown to reduce tumor volume and improve the survival of mice with subcutaneous B16F10 melanomas." (PMID 38892038, 2024). "In the melanoma tissue of the C57BL/6J mice, treatment with exogenous ARSB reduced the free galectin-3 (p < 0.0001)." (PMID 38892038, 2024). "In the human melanoma cell lines, expression of CSPG4 (chondroitin sulfate proteoglycan 4, also known as melanoma specific proteoglycan) increased following silencing of ARSB." (PMID 36361933, 2022). "In human melanoma cells, expression of pro-MMP2 and MMP-9 was increased following ARSB silencing and was mediated by decline in SHP2 activity and increase in phospho-ERK1/2." (PMID 36361933, 2022). "The combined effects of decline of ARSB and increase of C4S, CSPG4, and MMP2 significantly increased the invasiveness of the melanoma cells." (PMID 36361933, 2022). "Experiments presented in this report show how transcriptional events which follow decline in ARSB contribute to MMP activation and the invasive potential of melanoma cells through effects on SHP2 and phospho-ERK1,2." (PMID 27926479, 2017). "In this report, experiments assessed how Arylsulfatase B (ARSB; N-acetylgalactosamine-4-sulfatase) treatment might interact with Pembrolizumab and improve therapeutic responses in melanoma." (PMID 42306793, 2026). "The relationship between these ARSB-C4S-initiated transcriptional mechanisms and immune-mediated effects on melanoma tumor proliferation has not been addressed previously." (PMID 38892038, 2024). "ARSB activity declined from 138 ± 7 nmol/mg protein/h in the normal melanocytes to 71 ± 1 nmol/mg protein/h in the metastatic melanoma cell line (p < 0.001, 1-way ANOVA with Tukey-Kramer post-test for M0 vs. other cell lines)." (PMID 27926479, 2017). "Arylsulfatase B (ARSB; N-acetylgalactosamine 4-sulfatase) is reduced in several malignancies, but levels in melanoma have not been investigated previously." (PMID 27926479, 2017). "Decline in ARSB leads to reduced binding of galectin-3 with C4S and increased availability of galectin-3 for nuclear translocation and cooperation with AP-1 and Sp1 in promoter activation, for expression of genes such as Wnt9A in colonic epithelium, versican in prostate cells, and CSPG4 in melanoma." (PMID 36361933, 2022). "ARSB activity was reduced ~50% in melanoma cells compared to normal melanocytes." (PMID 27926479, 2017). "These associations between UV exposure, COP1, ETS1, BCL2, and melanoma apoptosis can provide new insight into fundamental melanoma pathophysiology, although no precise common mechanism between UVB exposure and decline in ARSB has been identified." (PMID 40562100, 2025).
prostate carcinoma (5 papers, 2017 to 2025). A carcinoma that arises from epithelial cells of the prostate gland. "Analysis of ARSB immunohistochemical staining of human prostate cancer tissue microarrays with nearly 300 cases indicated that the decline in ARSB was associated with prostate cancers of a higher Gleason grade and with earlier recurrence." (PMID 40362587, 2025). "Subsequently, analysis of ARSB immunochemistry in prostate cancer tissue microarrays including nearly 300 cases showed that lower ARSB intensity scores were associated with higher Gleason scores and with increase in biochemical recurrences." (PMID 36361933, 2022). "In our published reports, marked decline in arylsulfatase B (ARSB; N-acetylgalactosamine-4-sulfatase) was associated with earlier biochemical recurrences and with higher Gleason scores in prostate cancers." (PMID 32595831, 2020). "Less intense ARSB immunochemical staining was associated with more aggressive prostate cancers, with higher Gleason scores, and with earlier recurrence." (PMID 29245974, 2017). "In this report, we extend our previous findings about a role for ARSB deficiency in prostate cancer." (PMID 29245974, 2017). "The data which follow suggest that the occurrence of prostate cancer associated with defective CFTR may be related to a decline in ARSB and may be responsive to treatment by rhARSB." (PMID 40362587, 2025). "Other experiments showed decline in DKK3 expression in tissue from prostate cancers and in prostate stem cells following ARSB silencing." (PMID 36361933, 2022). "The overall reduction in the expression of ARS was found to be related to prostate cancer aggressiveness, due to the association between ARSB and the epidermal growth factor receptor (EGFR), commonly overexpressed when ARSB is reduced." (PMID 33445445, 2021). "In human prostate cancer tissues, the ARSB activity was reduced and the GALNS activity was increased, compared to normal prostate tissue." (PMID 29245974, 2017). "Decline in ARSB activity was demonstrated in human prostate cancer tissues and in prostate cancer tissue microarrays." (PMID 29245974, 2017). "This suggested that changes in ARSB and in C4S might contribute to increased proliferation in prostate cancer." (PMID 29245974, 2017).
Alzheimer disease (3 papers, 2022 to 2025). A progressive, neurodegenerative disease characterized by loss of function and death of nerve cells in several areas of the brain leading to loss of cognitive function such as memory and language. "Our data complement previous studies implicating ARSB variants in Alzheimer’s disease and Parkinson’s disease, expanding the pathogenic role of the gene in neurodegeneration." (PMID 38182665, 2024). "ARSB was mainly enriched in the lysosome, chemokine signaling pathway, spliceosome, Alzheimer’s disease, oxidative phosphorylation, Huntington’s disease, regulation of actin cytoskeleton, and Leishmania infection pathways." (PMID 40534738, 2025). "Decline in ARSB and the resulting increase in chondroitin 4-sulfate have been investigated in a wide range of neurological disorders, including spinal cord injury, peripheral nerve injury, optic nerve injury, traumatic brain injury, and Alzheimer’s Disease." (PMID 36361933, 2022).
asthma (2 papers, 2021 to 2022). "In the study of ARSB activity in peripheral leukocytes of cystic fibrosis patients 854, the subset of the controls with a diagnosis of asthma had reduced activity of neutrophil ARSB activity, compared to non-diseased controls." (PMID 36361933, 2022).
breast carcinoma (2 papers, 2018 to 2023). "KDM5B, ARSB, AKR1C3, HSD3B1, ESRRB are involved in steroid hormone metabolism and have been found to be associated with other hormone-dependent tumors, such as prostate and breast cancers." (PMID 36742386, 2023). "Furthermore, high CAP1 expression was associated with poor tumor characteristics and correlated with expression of genes and biological pathways within growth promoting (such as Abl, RRAGC and mTOR) and cell motility processes (e.g., Arp2/3 complex, ARSB and FN1) in breast cancer." (PMID 30524378, 2018).
colorectal cancer (2 papers, 2022 to 2023). A primary or metastatic malignant neoplasm that affects the colon or rectum. "Elevated Arylsulfatase B activity was detected in 71% of 24-h urine samples from 243 patients with colorectal cancer, but in studies of arylsulfatase in lung, liver, and kidney, the assay used did not distinguish ARSB from ARSA or ARSC (steroid sulfatase)." (PMID 36361933, 2022). "Decline in circulating RNA of ARSB was reported in 45 consecutive patients with colorectal cancers, compared to healthy controls." (PMID 36361933, 2022).